ITGA6 (integrin subunit alpha 6)
Diseases named in the same sentence as ITGA6 in open-access papers (continued):
Sharing a sentence is not in itself a finding about the gene and the disease.
glioblastoma (continued). "In glioblastoma, ITGA6 is more abundant in glioblastoma stem cells (GSCs) compared to non-glioma stem cells." (PMID 39239559, 2024). "Noteworthy, ITGA6 is important for maintaining stemness in pro-neural glioblastoma stem-like cells but not in mesenchymal glioblastoma stem-like cells." (PMID 37444576, 2023). "Upregulation of ITGA6 by MYC in CRC at the transcriptional level is consistent with the fact that MYC and ITGA6 have been found to be overexpressed separately in several types of cancers including breast and prostate cancers, liposarcoma and glioblastoma." (PMID 29401653, 2018). "Hence, CD44+/CD133+/ITGA6+/CD36+ is the core signature that is consistently present in all seven gliomasphere systems as the common consensus multi‐marker combination – irrespective of the origin of the gliomasphere (stem‐like cell line, traditional glioblastoma cell line or patient‐derived)." (PMID 30467961, 2019).
glioma (17 papers, 2011 to 2025). A benign or malignant brain and spinal cord tumor that arises from glial cells (astrocytes, oligodendrocytes, ependymal cells). "Based on data from The Cancer Genome Atlas, ITGA6 is assumed as an autophagy-related gene, and a Cox analysis indicated that autophagy-related risk scores of ITGA6 is a predictor of lower-grade gliomas and female lung adenocarcinoma patients." (PMID 37444576, 2023). "In a study on constructing a prognostic model for glioma based on ferroptosis-related genes, the model gene ITGA6 was verified to enhance cell proliferation, migration, and invasion." (PMID 40821828, 2025). "Analysis of TCGA datasets in glioma patients confirmed significant positive correlation of ITGA6 expression with CDK1, CDK4, PCNA, and FOXM1 transcript levels." (PMID 34205341, 2021). "The expression patterns of other glioma stem cell promoting proteins that were found in the list of deregulated genes, ITGA6 and BMI1, where variable." (PMID 29724193, 2018). "In addition, ITGA6 also participates in the tumour development and progression of lower-grade gliomas." (PMID 36835655, 2023). "Correlation analysis revealed that TSPAN4 was positively correlated with ITGB1, GDF15, ITGA3 and ITGA6, and negatively correlated with CHD7, ASPDH, TMEM8B and GHITM in glioma." (PMID 39723210, 2024). "Recurrent deletions in previously unknown glioma genes NT5C2, ADGRL2, and UIMC1 were observed whilst SUB1, CES1, and ITGA6 were frequently methylated in human LGGs; frequent CNVs in these genes were also present in human GBMs." (PMID 32727536, 2020).
ovarian carcinoma (16 papers, 2008 to 2025). A malignant neoplasm originating from the surface ovarian epithelium. "We propose that ITGA6 targeting, by specific blocking antibody, could be exploited to improve the effects of PT-based chemotherapy in high risk ovarian cancer patients and prevents the appearance of recurrent/resistant diseases." (PMID 38658801, 2024). "ITGA6 adhesion mediates drug resistance in ovarian cancer, indicating that its expression is upregulated in cisplatin-resistant cells." (PMID 37444576, 2023). "Itga6 is also regulated by miRNA-92a, as shown in ovarian cancer cell lines, repressing their proliferation and metastasis." (PMID 37444576, 2023). "Another miRNA, miR-506, has been shown to inhibit ovarian cancer progression by directly targeting the integrins ITGA6 and ITGB3, both of which are implicated in ovarian cancer cell migration, invasion, and survival." (PMID 37760437, 2023). "In ovarian cancer cells, overexpression of miR-506 significantly decreased ITGA6 and ITGB3 expression and led to reduced cell migration and invasion." (PMID 37760437, 2023). "On the other hand, Villegas–Pineda and collaborators reported that blocking ITGA6 decreases migration and invasion of ovarian cancer cells." (PMID 37444576, 2023). "In the case of ovarian cancer, there is contradictory information regarding the expression of ITGA6 and its possible effect." (PMID 37444576, 2023). "Utilizing public datasets, ITGA6 is found to be a good prognosis predictor in ovarian cancer." (PMID 37444576, 2023). "Upregulation of ITGA6 was reported in ovarian cancer, leading to multi-drug resistance." (PMID 34366863, 2021). "Among all analyzed integrin genes, we found increased ITGA3/A5/A10/A2B and ITGB3/B4/B8 expressions were significantly associated with poor OS, while decreased ITGA6/A7/AE and ITGB7 expression were significantly associated with poor OS in ovarian cancer patients." (PMID 32765584, 2020). "CD49f+, also known in the literature as integrin α-6 (ITGA6), is poorly studied in relation to ovarian cancers, but it is known that it is overexpressed in SK-OV-3 cisplatin-resistant cells." (PMID 39000063, 2024). "Genetic or pharmacological inhibition of ITGA6 reduces PT-res metastatic abilities and increases their sensitivity to PT both in vitro and in several in vivo PDX models of ovarian cancer." (PMID 38658801, 2024). "In particular, miR-29c is reported to target integrin alpha-6 (ITGA6), inhibiting ovarian cancer cell adhesion, migration, and invasion." (PMID 37760437, 2023). "MiR-127-3p acts as a tumor growth suppressor by targeting KIF3, ITGA6, and BAG5 in SCC, osteosarcoma, and ovarian cancer." (PMID 33396321, 2020).
melanoma (13 papers, 2019 to 2025). A malignant, usually aggressive tumor composed of atypical, neoplastic melanocytes. "In contrast, ITGA6 X2 variants are less frequent but more represented in skin-associated malignancies, such as basal cell carcinoma, squamous cell carcinoma, and melanoma, suggesting a possible link to basement membrane-related processes." (PMID 41153352, 2025). "Some studies found that tissues with gene variants of ITGA10 and ITGA6 were less susceptible to melanoma." (PMID 33335550, 2020). "The analysis of COSMIC histology annotations revealed that ITGA6 X1 mutations are distributed across multiple epithelial cancer types, including urinary tract, breast, lung, stomach, and large intestine carcinomas, as well as several melanomas." (PMID 41153352, 2025). "We confirmed the expression patterns of CLN6, GMPR, AP1S2, and ITGA6 in melanoma cells using gene-specific primers by qRT-PCR." (PMID 40821828, 2025). "When we assessed the association of TLR4, ITGA6, and BTG2 gene expression with melanoma prognosis, we observed that their higher expression (median cutoff) was significantly associated with a worse overall survival in TCGA SKCM cohort of 458 samples." (PMID 33980826, 2021). "From MetaCore network analysis, three hub genes (TLR4, ITGA6, and BTG2) were identified as targeted by multiple miRNAs, either up- or downregulated in multiple melanomas." (PMID 33980826, 2021). "Notably, we identified differentially expressed cell surface markers including MCAM (CD146), CSPG4, and ITGA6/ITGA7, which are well-established melanoma resistance markers." (PMID 41000875, 2025). "The role of ITGA6 in melanoma is not clear but our observation point toward its upregulation in MPMs upon miR-25 and miR-29 downregulation." (PMID 33980826, 2021).
pancreatic cancer (12 papers, 2018 to 2025). "It is reported that RPSA is highly expressed in the invasive human pancreatic cancer cell line PC-1.0 and is linked to Integrin α 6 (ITGA6), a protein involved in the regulation of cell–cell attachment." (PMID 34873618, 2021). "ITGB1 and ITGA6 present on pancreatic cancer-derived EVs were found to control the EV tropism toward adipocytes where these EVs stimulate lipolysis via the cyclic adenosine monophosphate (cAMP)-PKA)-HSL pathway." (PMID 37998333, 2023). "It has been discovered that higher levels of Integrin alpha 6 (ITGA6) are expressed in the highly invasive pancreatic cancer cells than in less invasive cells, resulting in a poor prognosis in pancreatic patients via TCGA." (PMID 34540825, 2021). "Knockdown of RPSA and ITGA-6 inhibits these pathways and leads to a reduction in pancreatic cancer cell line invasion and metastasis." (PMID 34873618, 2021). "ITGA3 and ITGA6, both members of the integrin signaling pathway, are overexpressed in pancreatic cancer." (PMID 29764514, 2018). "In both methods of analysis, ITGA6 is overexpressed in head and neck, lung, liver, and pancreatic cancers." (PMID 30046394, 2018). "As to integrins, ITGA6 and ITGB4 are integrins that are highly expressed in pancreatic cancer stem‐like cells, contributing to tumor aggressiveness, treatment resistance, and metastatic dissemination." (PMID 40952239, 2025). "From a mechanistic point of view, proteomic analysis performed in pancreatic cancer cells, revealed that RPSA interacted with Integrin alpha 6 (ITGA6) and that they colocalized on the plasma membrane as showed by immunofluorescence analysis." (PMID 37452879, 2023). "For instance, ITGA6 synergistically interacted with RPSA to promote cell migration and invasion in pancreatic cancer." (PMID 33317527, 2020). "Another interesting study conducted by Shibata and colleagues found that pancreatic cancer-derived EVs carry adipocyte-targeting integrins, integrin subunit beta 1 (ITGB1) and integrin subunit alpha 6 (ITGA6), that aid in inducing lipolysis during pancreatic cancer-associated cachexia." (PMID 37998333, 2023). "ITGA6 promotes the activation of PI3K after regulating the phosphorylation level of AKT, while RPSA activates MAPK signaling pathway which consequently stimulates the invasion and the metastasis of pancreatic cancer cells." (PMID 34873618, 2021).
hepatocellular carcinoma (10 papers, 2018 to 2025). A malignant tumor that arises from hepatocytes. "This study aims to validate the integrin alpha-6 (ITGA6) gene as a potential blood marker for early detection of hepatocellular carcinoma (HCC)." (PMID 37627184, 2023). "For example, ITGA6 is significantly overexpressed in hepatocellular carcinoma and mediates tumor progression." (PMID 36406077, 2022). "For example, ITGA6 is vital for the proliferation and maintenance of EVI1-high acute myeloid cell lines, while another example is the direct interaction and reciprocal regulation between ITGA6 and PSMC2, which interferes with the growth and progression of hepatocellular carcinoma." (PMID 37444576, 2023).
osteosarcoma (10 papers, 2014 to 2025). A usually aggressive malignant bone-forming mesenchymal neoplasm, predominantly affecting adolescents and young adults. "Our research has identified the key molecule THBS1, along with its downstream targets ITGA1 and ITGA6, which play a role in the dedifferentiation of osteosarcoma cells." (PMID 40083708, 2025). "Co-IP experiments confirmed the interaction between THBS1 and ITGA1/ITGA6 in the dedifferentiation of osteosarcoma cells." (PMID 40083708, 2025). "PSMC2 likely drives osteosarcoma via its regulation of cancer-related genes, including ITGA6, FN1, CCND1, CCNE2 and TGFβR210." (PMID 31598166, 2019). "miR-127-3p targets ITGA6 to affect the proliferation and invasion of osteosarcoma cells." (PMID 40757880, 2025). "In addition, SNHG16 has be suggested to promote EMT by upregulating ITGA6 through a miR-488 inhibition in osteosarcoma." (PMID 34458149, 2021). "However, the role of THBS1 in promoting osteosarcoma pulmonary metastasis could be reversed by ITGA1 or ITGA6 knockdown." (PMID 40083708, 2025). "Our results also demonstrated that ITGA1 and ITGA6, two subunits of integrin, play a role in mediating extracellular signals in cells and that THBS1 promotes the dedifferentiation and metastasis of osteosarcoma cells." (PMID 40083708, 2025). "In addition, during the sphere formation of osteosarcoma cells, the signal intensity of ITGA1 and ITGA6 on the cell membrane surface at the outer edge of the sphere was higher than that inside the sphere, and colocalization with THBS1 also occurred in cells at the outer edge of the sphere." (PMID 40083708, 2025).
breast tumor (9 papers, 2010 to 2024). "Since ITGA6 expression and a HIF transcriptional core gene signature are enriched in basal-like breast tumors relative to luminal (ER+) tumors, we sought to determine if ITGA6 might also be a direct HIF target gene." (PMID 27001172, 2016).
gallbladder carcinoma (8 papers, 2018 to 2023). "Human miR-143-3p can suppress tumor angiogenesis and growth of gall bladder carcinoma through ITGA6/PI3K/AKT/PLGF pathways." (PMID 30619741, 2018). "Itga6 is an essential marker gene for pluripotent cells of the hair follicle, which influences the balance between stem cell renewal and differentiation and is targeted by miR-143-3p in human gallbladder carcinoma to suppresses tumor growth and angiogenesis." (PMID 36674578, 2023). "Moreover, the overexpression of ITGA6 suggests a poor prognosis in breast, colorectal, kidney, and gallbladder cancers." (PMID 36268277, 2022). "ITGA6 is a potential clinical prognostic marker for gallbladder carcinoma." (PMID 33540700, 2021). "Integrin 6 (ITGA6), targeted by miR-143-3p, impedes the PI3K/AKT pathway to elicit gallbladder cancer growth and angiogenesis." (PMID 34983307, 2022). "Importantly, a very recent study showed that miR‐143‐3p targeting of ITGA6 was involved in tumor growth and angiogenesis by downregulating PLDF expression in gallbladder carcinoma." (PMID 36708044, 2023).
kidney cancer (7 papers, 2016 to 2025). Primary or metastatic malignant neoplasm involving the kidney. "It has been reported that Twist2 promoted kidney cancer cell proliferation and invasion by upregulating ITGA6 expression in the ECM-receptor interaction pathway." (PMID 31832114, 2019). "Our finding on decreased ITGA6 levels raise the possibility that enhanced dissemination of kidney cancer cells could in part explain the aggressive pathogenesis of PRCC2." (PMID 27705936, 2016). "Twist2 is known to regulate ITGA6 and CD44 expression in the ECM-receptor interaction pathway to promote kidney cancer cell proliferation and invasion." (PMID 41450820, 2025). "A study reported that Twist2 regulates the expressions of CD44 and ITGA6 in the ECM-receptor interaction pathways, thereby stimulating the invasion and proliferation of kidney cancer cells." (PMID 35028418, 2022).
leukemia (7 papers, 2012 to 2025). A malignant (clonal) hematologic disorder, involving hematopoietic stem cells and characterized by the presence of primitive or atypical myeloid or lymphoid cells in the bone marrow and the blood. "Notably, ITGA6 expression is negatively associated with white blood cell count, as is characteristic of the B-other cytogenetic leukemia category, which cannot be categorized into any of the known cytogenetic groups." (PMID 37444576, 2023). "One study in a mouse model of BCR-ABL positive leukemia with CNS tropism found the upregulation of L-selectin and integrin subunit alpha 6 (Itga6) in BCR-ABL expressing cells compared to control cells." (PMID 31970588, 2020). "ITGB1, ITGB3, ITGA4, and ITGA5 were expressed in five of the six leukemia cell lines, and ITGB4 and ITGA6 were specifically expressed in the three EVI1high leukemia cell lines." (PMID 22295105, 2012). "We found that the EVI1high leukemia cells with increased ITGA6 and ITGB4 expression exhibited stronger adhesion to laminin complexes than the EVI1low leukemia cells; although, the EVI1low leukemia cells exhibited increased adhesion to fibronectin." (PMID 22295105, 2012). "ITGB1 and ITGA4 were expressed as very late antigen-4 (VLA-4) in most of the cell lines, but ITGB4 and ITGA6 were expressed in all three leukemia cell lines and in the two primary EVI1high leukemia cell lines." (PMID 22295105, 2012). "Using DNA microarray analysis, we previously identified that integrin α6 (ITGA6) was upregulated over 10-fold in EVI1high leukemia cells." (PMID 22295105, 2012). "To confirm the ITGA6 dependence of the increased cell adhesion of EVI1high leukemia cells, we used a series of neutralizing antibodies." (PMID 22295105, 2012). "We found that the adhesion ability of EVI1high leukemia cells to laminin increased with the increased expression of ITGA6 and integrin β4 (ITGB4)." (PMID 22295105, 2012). "We identified ITGA6 in 26 selected genes that were upregulated over ten-fold in EVI1high leukemia cells (p<0.01)." (PMID 22295105, 2012). "The introduction of small-hairpin RNA against EVI1 (shEVI1) into EVI1high leukemia cells reduced the cell adhesion ability and downregulated the expression of ITGA6 and ITGB4." (PMID 22295105, 2012). "Finally, drug sensitivity is restored in EVI1-high leukemia cells treated using ITGA6-neutralizing antibodies or short hairpin RNA against evi1." (PMID 37444576, 2023). "Moreover, treating EVI1high leukemia cells with neutralizing antibodies against ITGA6 or ITGB4 resulted in an enhanced responsiveness to anti-cancer drugs and a reduction of their cell adhesion ability." (PMID 22295105, 2012). "Because the EVI1high leukemia cells exhibited an increased adherence to the murine osteoblastic cell line MC3T3-E1 we examined whether this adhesion was dependent on ITGA6 or ITGB4 expression by treating with a neutralizing antibody." (PMID 22295105, 2012). "As a corollary, the increased expression of the ITGA6/ITGB4 complex in EVI1high leukemia might be an important factor in maintaining leukemia stem cells in the bone marrow." (PMID 22295105, 2012). "Because similar results were also obtained using the anti-cancer drug, VP-16, the treatment with anti-ITGA6 or anti-ITGB4 antibodies or anti-cancer drugs might recover the drug-sensitivity of EVI1high leukemia cells." (PMID 22295105, 2012). "In addition, the overexpression of EVI1 in EVI1low leukemia cells enhanced their cell adhesion ability and increased the expression of ITGA6 and ITGB4." (PMID 22295105, 2012). "Moreover, increased expression of ITGA6 was shown to be correlated with the development of oesophageal cancer; and increased aggressiveness, drug resistance and poor prognosis has been correlated with the presence of ITGA6 in leukemia." (PMID 23570247, 2013).